CXCL1 (C-X-C motif chemokine ligand 1)
Diseases named in the same sentence as CXCL1 in open-access papers (continued):
Sharing a sentence is not in itself a finding about the gene and the disease.
viral infection (continued). "The chemokines, CXCL-1 and G-CSF, which are expressed by macrophages, neutrophils, and epithelial cell, can attract other non-hematopoietic cells to the viral infection sites, playing an important role in regulating immune and inflammatory responses." (PMID 38316817, 2024). "Since CXCL1 and CXCL2/3, acting through CXCR2, are potent neutrophil chemoattractants, we investigated their role in dsRNA-induced lung injury, where dsRNA (Poly IC) is a well-described synthetic agent mimicking acute viral infection." (PMID 15921526, 2005). "Even though CLEC2.Fc was unable to inhibit virus infection and replication, CLEC2.Fc inhibited the expression of IL‐6, CXCL2, CXCL5, CCL2, and IP‐10 at day 3 and day 5 post‐infection, and the expression of TNF‐α, IFN‐γ, IL‐10, and CXCL1 was also suppressed at day 5 post‐infection (red columns)." (PMID 37211986, 2023). "Indeed, CXCL10 was reported to be a key regulator of the cytokine storm in SARS-CoV-2 infection, CXCL1 to play a role in chemotactic neutrophils in bacterial infections, and OASL to be involved in IFN-gamma signaling and PI3K-Akt signaling pathways, which can restrict virus infection." (PMID 34899651, 2021). "Hierarchical clustering identified a distinctive innate immune signature in bite sites that was dominated by neutrophil-attracting chemokines (CXCL1, CXCL2, CXCL3, and CXCL5) and the cytokines IL-1β and IL-6, which were not significantly induced by virus infection alone." (PMID 27332734, 2016).
pneumonia (32 papers, 2012 to 2025). An acute, acute and chronic, or chronic inflammation focally or diffusely affecting the lung parenchyma, caused by an infection in one or both of the lungs (by bacteria, viruses, fungi, or mycoplasma.). "Pneumonia induced by K. pneumoniae or LPS is associated with the overproduction of IL-1β and neutrophil-related chemokines such as CXCL1, CXCL2, and CXCL6." (PMID 35682923, 2022). "In contrast to homeostatic conditions, we report an increase in cytokine expression during pneumonia in the Zcchc6-deficient mice compared to wildtype controls, particularly IL-6 and CXCL1." (PMID 28665939, 2017). "Previous results showed that Adh was involved in pleuropneumoniae-mediated CXCL1 release in mice, which led us to speculate that CXCL1 was the main factor causing pneumonia." (PMID 27046446, 2016). "CXCL1 has been shown to be critical for the homing of neutrophils to the lung in pneumonia, suggesting that chemokine production by neutrophils themselves is likely contributing to additional cellular recruitment to the lung in age." (PMID 35392033, 2022). "The role of CXCL1 in the pathophysiology of bacterial-induced pneumonia was demonstrated using CXCL1-/- mice." (PMID 36164329, 2022). "MCTR-exposed rAMs had increased migration and phagocytosis of Streptococcus pneumoniae, reduced secretion of CXCL1, and a reversion toward baseline levels of several IAV-induced pneumonia susceptibility genes." (PMID 35913160, 2022). "Neutrophils are attracted to the airways by locally released CXC chemokines such as CXCL1 and play a key role in host defense during pneumonia." (PMID 33793661, 2021). "The CXCL1 regulates neutrophil infiltration and the bacterial clearance during K. pneumoniae-induced pneumonia via regulating the CXCL2/MIP-2 and CXCL5, and NF-κB and MAPKs activation in the lungs." (PMID 32849610, 2020). "The main phenotype of Clca1−/− mice in a model of S. aureus-induced pneumonia consisted of reduced activation of CXCL-1 and IL-17A expression and decreased neutrophilic infiltration into the bronchoalveolar space." (PMID 29610986, 2018). "Lung neutrophils from mice with pneumonia showed increased expression of genes that encode a number of mediators, including the important pro-inflammatory cytokines IL-1α, IL-6, TNF and CXCL1 (KC)." (PMID 28900269, 2017). "Using a murine model of pneumonia, we found that siderophore secretion by K. pneumoniae induces the secretion of interleukin-6 (IL-6), CXCL1, and CXCL2, as well as bacterial dissemination to the spleen, compared to siderophore-negative mutants at an equivalent bacterial number." (PMID 27624128, 2016). "Studies have shown that propionate mitigates pneumonia severity and lung tissue remodeling by reducing the infiltration of neutrophils, eosinophils, and lymphocytes, and by interfering with the release of chemokine C-X-C Motif Chemokine Ligand 1(CXCL1) and inflammatory factor TNF-α." (PMID 40647346, 2025). "To obtain an initial understanding of how SRT1720 affects the inflammatory response in the airways during Klebsiella-induced pneumonia, we measured cytokines (IL-6, TNF-α) and chemokines (CXCL1 and CXCL2) in BALF obtained 24 or 42 h after infection." (PMID 41096578, 2025). "MRSA-induced pneumonia feces recipients exhibited a trend toward higher bronchoalveolar lavage fluid (BALF) TNF-α, IL-6, IL-1β, CXCl-1, MCP-1 levels, and W/D ratio." (PMID 37823635, 2023). "Pre-existing T. spiralis infection decreased lung neutrophil recruitment, inflammatory mediator IL-1β and IL-6 expression and chemokine CXCL1 and CXCL2 release during P. aeruginosa- pneumonia." (PMID 35500031, 2022). "For instance, in the lung, only three groups with LPS-induced pneumonia (LPSPn, SOS + LPSPn, and DSS + SOS + LPSPn) had elevated pulmonary CXCL1 expression and number of neutrophils, while the other groups did not." (PMID 34336855, 2021).
pneumonia (continued). "We next assessed the contribution of IL-1β, CXCL1, CCL2, and CCL7 to the recruitment of neutrophils during S. pneumoniae pneumonia using specific neutralizing Abs administered intranasally." (PMID 25948816, 2015). "Furthermore, we analyzed CXCL1 chemokine levels in plasma and BALF obtained from K. pneumonia-treated mice and found significantly increased chemokine levels upon pneumonia compared to baseline conditions." (PMID 40413164, 2025). "Our finding that pro-inflammatory gene expression is stronger in BALB/c mice is in line with several previous studies that compared C67Bl/6 and BALB/c mice: After infection with mcyoplasma pneumonia, the BAL levels of CXCL1, MIP-1α, MCP-1, IL-1b and IL-6 were higher in BALB/c mice." (PMID 22848503, 2012). "Furthermore, exogenous administration of recombinant human TRX significantly improved the survival rate and attenuated the histological changes in lungs in a mouse model of influenza pneumonia by diminishing the production of TNF-α and CXCL1 in the lungs observed in influenza-inoculated mice." (PMID 32244938, 2020). "The pleural levels of Groα/CXCL1 and Groβ/CXCL2 in pneumonia patients have not been investigated previously; the role of these two cytokines may need further study." (PMID 33469074, 2021). "In the absence of CXCL5, CXCL1, and CXCL2 bind to the Duffy Antigen Receptor for Chemokines (DARC) to increase the neutrophil infiltration in the lungs, which enhances bacterial clearance, and protects the animal from severe pneumonia." (PMID 32849610, 2020).
bladder cancer (31 papers, 2013 to 2025). "It has been reported that the CXCL1-mediated interaction of cancer cells with tumor-associated macrophages promotes tumor progression in bladder cancer." (PMID 38713320, 2024). "CXCL1 is also responsible for the recruitment of MDSCs to the bladder cancer niche, cells that cause cancer immune evasion and resistance to chemotherapy." (PMID 38673949, 2024). "In bladder cancer, the production of CXCL1 in tumor-associated macrophages supported tumor implantation in the wall of the murine bladder." (PMID 34269159, 2021). "What is more important, high CXCL1 level in bladder cancer tissue was positively associated with increased TAMs infiltration and higher pathologic stages in bladder cancer." (PMID 31803057, 2019). "CXCL1 is also overexpressed in human bladder carcinomas, and this increased expression is associated with a higher bladder carcinoma grade and stage." (PMID 27682863, 2016). "Our study demonstrated that CXCL1 protein is specifically expressed in human bladder carcinomas and that increased expression is associated with high-grade and high stage BCa, and with reduced DSS." (PMID 23815949, 2013). "Also, the release of CCL2, CXCL1, and Il-6 by CAAs is associated with bladder cancer cell migration." (PMID 40076892, 2025). "CXCL1 derived from TAMs and cancer associated fibroblasts could promote the invasion and colonization of bladder cancer cells." (PMID 32213179, 2020). "Recently, several studies have linked CXCL1 expression to bladder cancer (BCa)." (PMID 26543745, 2015). "CXCL1 is a strategic player in bladder cancer, supporting repeated intravesical recurrence and disease progression." (PMID 40076892, 2025). "The same mechanism of increased CXCL1 expression has been observed for epidoxorubicin acting on bladder cancer cells." (PMID 40427171, 2025). "CXCL1 from bladder cancer tumors makes its way into the urine and for this reason, patients with this cancer have elevated levels of this chemokine in their urine compared to healthy individuals." (PMID 38673949, 2024). "CXCL1 is important in tumorigenesis in bladder cancer, as it induces the proliferation of cancer cells." (PMID 38673949, 2024). "Some anticancer drugs, such as epidoxorubicin, increase CXCL1 expression in bladder cancer cells, which leads to the EMT of cancer cells and the production of metastasis as a side effect of therapy." (PMID 38673949, 2024). "Intriguingly, C-X-C motif chemokine 1 (CXCL1) has been identified to be increased in aggressive bladder cancer and correlated with TAM recruitment, a role also played by CXCL12." (PMID 38542388, 2024). "Mechanistically, transcription factor ETV4 enhances bladder cancer cells-derived CXCL1/8 to recruit TANs, increasing VEGFA and MMP9 secretion from TANs to promote lymphangiogenesis and lymphatic metastasis of bladder cancer." (PMID 39726782, 2024). "An example of this is HL2401, a monoclonal antibody anti-CXCL1, which inhibits the proliferation and migration of bladder cancer cells, as well as bladder cancer tumor growth in an in vivo model." (PMID 38673949, 2024). "A higher level of CXCL1 protein expression was found in human bladder cancers with aggressive phenotypes." (PMID 36614235, 2023). "The value of urine CXCL1 concentration normalized by urine creatinine (CXCL1/Cre) was demonstrated to have great advantage in predicting post-transurethral resection recurrence of bladder cancer patients." (PMID 36612163, 2022). "In vivo, CXCL-1 was shown to collaborate with IL-6 to activate endothelial cells and to promote angiogenesis in bladder cancer." (PMID 33267794, 2020). "In bladder cancer, urinary CXCL1 levels were significantly higher in patients with invasive bladder cancer than those with noninvasive tumors and normal controls, indicating CXCL1 was an independent factor for predicting bladder cancer invasion." (PMID 31803057, 2019).
bladder cancer (continued). "Studies have linked CXCL1 expression to gastric, colon and skin cancers, but limited studies to date have described CXCL1 protein expression in human bladder cancer (BCa)." (PMID 23815949, 2013). "Herein, we report the largest study assessing CXCL1 expression patterns in human bladder cancer (BCa) tissues." (PMID 23815949, 2013). "For this reason, drugs targeting CXCL1 have anti-tumor effects on bladder cancer." (PMID 38673949, 2024). "At the same time, CXCL1 levels are higher in basal type than in luminal type bladder cancer." (PMID 38673949, 2024). "In bladder cancer tumors, the expression of CXCL1 is elevated." (PMID 38673949, 2024). "In the bladder cancer niche, CXCL1 is produced by cancer cells." (PMID 38673949, 2024). "In bladder cancer, the CXCL1-mediated interaction of tumor cells with CAFs promoted tumor growth." (PMID 36439880, 2022). "This was in consistent with the existing report that CXCL1-mediated interaction between TAMs and cancer cells could promote tumor progression in human bladder cancer." (PMID 31803057, 2019). "Interestingly, CXCL1 levels in bladder cancer tissue were positively associated with TAM infiltration, and CXCL1-expressing TAMs enhanced bladder cancer growth when injected together in nude mice." (PMID 30158589, 2018). "Radiation therapy may elevate the expression of CXCL1 in bladder cancer cells." (PMID 38673949, 2024). "It appears that CXCL1 and PAI1 secreted by adipose tissue and bladder-derived ASCs play an important role in inducing the migration of bladder cancer cells." (PMID 29887999, 2018). "Some researchers have reported that the expression of CXCL1 and CXCL2 is correlated with tumor size, metastasis, and decreased overall survival in breast, gastric, colorectal, hepatocellular, and bladder carcinoma patients." (PMID 29703902, 2018). "Exogenous treatment of T24 bladder cancer cells using recombinant human IL6, PAI1, or CXCL1 enhanced their migratory potential." (PMID 29887999, 2018).
cervical cancer (29 papers, 2014 to 2025). A primary or metastatic malignant neoplasm involving the cervix. "In cervical cancer, upregulation of CXCL1/CXCL2 is associated with malignant tumor phenotypes (larger tumor size, lymph node (LYN) metastasis, and shorter patient survival)." (PMID 36612163, 2022). "The immune checkpoint gene CXCL1 shows statistically significant differences between subtype A (Cluster 1) and subtype B (Cluster 2) in cervical cancer (CESC) samples (p value < 0.001)." (PMID 40438679, 2025). "In the multivariate Cox regression, N1 stage, high-risk score, and the genes TNF, ITGA5, CXCL1, and CCL20 were observed to be significantly associated with increased risk in cervical cancer patients." (PMID 40517358, 2025). "CircRNF13 is a novel circRNA regulated by m6A modifications that specifically down-regulates the expression of CXCL1 in cervical cancer." (PMID 39972266, 2025). "In cervical cancer, CXCL1 promotes tumor cell migration and invasion through its receptor CXCR2 while modulating the immune microenvironment to suppress anti-tumor immune responses." (PMID 40517358, 2025). "The immune checkpoint gene CXCL1 displayed highly significant statistical differences between subtype A (Cluster 1) and subtype B (Cluster 2) in cervical cancer (CESC) samples." (PMID 40438679, 2025). "METTL3 promotes m6A methylation and degradation of circRNF13, which leads to increased expression of CXCL1 and enhances radioresistance in cervical cancer." (PMID 39972266, 2025). "Upregulation of CXCL1 in cervical cancer cells is responsible for promoting angiogenesis and tumor growth." (PMID 38536591, 2024). "The degradation of CircRNF13 is regulated by METTL3/YTHDF2, which subsequently influences the stability of CXCL1 and contributes to the enhancement of radiosensitivity in cervical cancer cells." (PMID 38651153, 2024). "The novel m6A-modified circular RNA, CircRNF13, was found to exhibit high expression levels in radioresistant cervical cancer tissues and was observed to enhance radiation resistance by upregulating the stability of CXCL1 mRNA." (PMID 38651153, 2024). "NF-κB attaches to the CXCL1 promoter, increasing the expression of CXCL1, which is produced and secreted by cervical cancer cells and then acts on these cells." (PMID 37108425, 2023). "In cervical cancer, the transcription level of CXCL1/3/5/6/8/9/10/11/13/16/17 is significantly increased, which is associated with poor prognosis." (PMID 35468838, 2022). "The transcriptional level of CXCL1/3/5/6/8/9/10/11/13/16 in cervical cancer tissues was significantly elevated, while the transcriptional level of CXCL12/14 was significantly lower than that of adjacent cancer tissue." (PMID 34321012, 2021). "It is therefore very probable that the copious PGE2 found in SF can mediate CXCL1 induction in neoplastic cervical cancer cells." (PMID 27446968, 2016). "As previously shown, CXCL1 is a useful marker in ovarian and cervical cancer and plays a role as a regulator of tumor homeostasis and vascularization and is a good marker for tumor-mediated systemic inflammation." (PMID 27190986, 2016). "Among the cytokines upregulated by the tumor microenvironment, we found IL-8 and CXCL1, which display redundant activities, chemoattracting neutrophils, inducing angiogenesis, cell survival and tumor evasion, including in patients with cervical cancer." (PMID 25400927, 2014). "M2 macrophages enhance cervical cancer cell migration and invasion by secreting CXCL1." (PMID 40005151, 2025). "Additionally, CXCL1 levels in the serum of cervical cancer patients are higher than in healthy subjects." (PMID 37108425, 2023). "However, the expression pattern and clinical significance of CXCL1 in human uterine cervix cancer (UCC), as well as its roles and mechanisms in UCC tumor biology remains entirely unclear." (PMID 35764974, 2022).
cervical cancer (continued). "Moreover, CXCL1 is a main factor in the development of cervical cancer as the increased level of CXCL1 was reported in serum of patients with cervical cancer in comparison to premalignant and healthy controls." (PMID 34246302, 2021). "Therefore, AKIP1 is critical to the angiogenesis and growth of cervical cancer by increasing levels of the NF-κB-dependent chemokines CXCL1, CXCL2, and CXCL8." (PMID 34833360, 2021). "AKIP1 in cervical cancer cells stimulates the expression of CXCL1, CXCL2, and CXCL8." (PMID 34833360, 2021). "Additionally, CXCL1 has been shown to be upregulated in cervical cancer, triggering EMT." (PMID 40813994, 2025). "CXCL1 may be important in the development of cervical cancer in pre-cancerous cervical lesions." (PMID 37108425, 2023). "This study revealed that the presence of HPV16 and 18 oncogenes significantly alter the expression of CCL28, CXCL1, CXCL2, CXCL3, CXCL6, CXCL8, CXCL10, and CXCL11; overexpression of those chemokines was also confirmed in cervical cancer biopsies." (PMID 37893029, 2023). "Epiregulin was positively correlated with most chemokines, such as CXCL1, CXCL2, CXCL3, CXCL5, CXCL6, CXCL8, and CCL20, in most types of cancer, including cervical cancer." (PMID 37020674, 2023). "For example, the increase of CXCL1/2/8 level regulated by AKIP 1 played an important role in the angiogenesis and growth of cervical cancer." (PMID 34321012, 2021). "SF regulated the expression of chemokines CCL2, CCL5, CXCL1, CXCL2, CXCL3, CXCL8 (IL-8), and CXCL11 all of which play vital role in cervical cancer inflammation and tumorigenesis." (PMID 27446968, 2016). "For instance, in cervical cancer, TNF activates the NF-κB signaling pathway, inducing the expression of chemokines such as CXCL1 and CXCL8, which promotes the infiltration of neutrophils and macrophages, thereby facilitating tumor progression and immune evasion." (PMID 40517358, 2025). "Our results revealed that expression of CXCL1, CXCL2, CXCL3, and CXCL8 increases in the presence of E6/E7 of HPV16 and 18, are overexpressed in CC biopsies, and that their higher expression is related to a worse prognostic survival in cervical cancer." (PMID 37893029, 2023). "It is reported that CXCL1, CXCL2, and CXCL8 are related to the tumor growth in cervical cancer." (PMID 36284631, 2022).